TCF4 (transcription factor 4)
Diseases named in the same sentence as TCF4 in open-access papers (continued):
Sharing a sentence is not in itself a finding about the gene and the disease.
glioma (30 papers, 2012 to 2024). A benign or malignant brain and spinal cord tumor that arises from glial cells (astrocytes, oligodendrocytes, ependymal cells). "Elevated expression of canonical Wnt factors (WNT3A, TCF4) correlates with higher glioma grades and poor outcomes." (PMID 39568072, 2024). "miR-137 is a well-known suppressor of cell proliferation, mainly by regulating the cell cycle and enhancing differentiation of glioma stem cells via its downstream targets, such as Clcl12, Cox2, Pdgfr, Sp1, Tcf4 and/or Cdk6." (PMID 38138985, 2023). "The authors further suggested that GRβ acts as a transcription co-factor of TCF-4 in the Wnt signaling pathway to regulate glioma cell proliferation." (PMID 33807481, 2021). "In contrast, IDH1 (R132H) mutation in gliomas, negatively regulates CD47 gene transcription, which disrupts the binding of PKM2/β-catenin/BRG1 complex to TCF4 transcription factor resulting in inhibition of TCF4-mediated CD47 expression." (PMID 34512146, 2021). "For example, the in vitro and in vivo experiments found that TCTP activated the binding of TCF-4 and β-catenin and then increased glioma cell growth." (PMID 33002062, 2020). "Through binding to β-catenin, Linc00320 inhibits Wnt/β-catenin signaling by disrupting β-catenin binding to TCF4 in Glioma cells." (PMID 33505307, 2020). "TCTP directly interacts with TCF4 and enhances the binding affinity of β-catenin to TCF4, leading to the expression of Wnt target genes and glioma cell proliferation." (PMID 28430641, 2017). "Taken together, it was suggested that the activating effects of ING5 on both PI3K/Akt and β-catenin/TCF-4 signal pathways contributed to chemotherapeutic resistance in glioma cells." (PMID 28915612, 2017). "A recent report shows that a significant reduction of AKT2 levels and phosphorylation of Akt was detected after knockdown of Tcf-4 using Tcf-4 siRNA in glioma cells." (PMID 23029137, 2012). "Glioma cell proliferation and invasion are maintained by β-catenin/TCF4 activity." (PMID 37509281, 2023). "TCF4 in glioma cells mainly acts in the Wnt/β-catenin-signaling pathway and interacts with TRIB2." (PMID 36231068, 2022). "In addition, FOXM1 interacts with β-catenin and promotes β-catenin/TCF4-dependent transcription in glioma cells." (PMID 34117362, 2021). "Furthermore, β-catenin increase markedly facilitated RMRP expression by TCF4 and TCF4 promoted RMRP expression by directly binding with the RMRP promoter region in glioma cells." (PMID 34657141, 2021). "Likewise, AKT1 and AKT2 found to be related to bcatenin/Tcf-4 signaling pathway that promoted malignant transformation in human LN229 glioma cell line." (PMID 29890617, 2018). "TCF-4 was elevated with increased pathological grade of glioma, and reduction of TCF-4 could suppress glioma growth both in vitro and in vivo, indicating TCF-4 plays an important role in glioma progression and prognosis." (PMID 27013586, 2016). "Thus, we further investigated whether β-catenin could regulate lncRNA RMRP expression by TCF4 in glioma cells." (PMID 34657141, 2021). "Indeed, several studies have revealed that the expression and nuclear localisation of β-catenin and its transcription factor TCF4 are significantly higher in glioma compared to that in normal brain tissue, and these characteristics positively correlate with the glioma grade." (PMID 30691485, 2019). "Indeed, several studies revealed that the expression and nuclear localization of β-catenin and its transcription factor TCF4 are significantly higher in glioma compared to normal brain tissue, and these findings positively correlate to World Health Organization (WHO) glioma grade." (PMID 29462960, 2018). "Distal enhancer on 8q24 mediates MYC transcription through beta catenin/TCF4 signaling, and silencing of FAM84B markedly reduced the level of active beta catenin and the transcription activity of TCF/LEF in glioma." (PMID 38997648, 2024).
glioma (continued). "In order to test the clinical relevance of our findings, we stained by immunohistochemistry (IHC) 128 samples retrieved from 87 glioma patients for the expression of HIF-1α, TCF1, TCF4 and the neuronal marker βIII-tubulin." (PMID 31410187, 2019). "In summary, our study provides new insights into the role of miR-19a/b in human glioma and confirms that miR-19 is able to inhibit RUNX3 expression level through directly binding to the 3′UTR region of RUNX3 which medicates the suppression of β-catenin/TCF4 transcription." (PMID 29340016, 2017).
autism (25 papers, 2013 to 2025). Persistent deficits in social interaction and communication and interaction as well as a markedly restricted repertoire of activity and interest as well as repetitive patterns of behavior. "In particular,heterozygous mice deficient in the Tcf4 transcription factor,which demonstrate features of autism, showed an increasedsynaptic transmission in the CA1 region of the hippocampus." (PMID 35975241, 2022). "The female-specific gene TCF4 is a reported autism-associated gene and is associated with coregulation of androgen receptor activity." (PMID 32066658, 2020). "Forty-three percent of patients with 18q deletion were categorised to be at risk of autism and the likelihood was significantly increased when TCF4, NETO1 and FBXO15 were included in the region of hemizygosity." (PMID 27271878, 2016). "TCF4 (autism- and SZ-associated) was the most “isoformic” disease gene in both human (n = 33 isoforms) and mouse (n = 57 isoforms) cortex; of note, both genes have been shown to be key members of transcriptional networks associated with neuropsychiatric disease." (PMID 34788620, 2021). "In addition to PTHS, balanced chromosomal abnormalities disrupting TCF4 and copy number variants have been found in patients with autism and neurodevelopmental disorders that were previously undiagnosed with PTHS." (PMID 24058414, 2013). "Among these, three (PAX6, TCF4, and ZMIZ1) are ASD risk genes according to the Simons Foundation Autism Research Initiative (SFARI) gene database." (PMID 35942939, 2022). "Four genes in our candidate list for autism (MAP1LC3B, PDE4B, TCF4 and UPF2) have already been associated with ASD." (PMID 26731442, 2016). "Four of the Root 66 genes (MAP1LC3B, PDE4B, TCF4 and UPF2) have previously been associated with autism, and 56 either have been shown to interact directly with known autism candidates or have been implicated in other autism-related neurological disorders." (PMID 26731442, 2016). "Furthermore, if the TCF4, NETO1, and FBXO15 genes were in the region of hemizygosity, the risk of autism increased significantly." (PMID 35056323, 2021).
depression (22 papers, 2015 to 2025). "For example, while SPPL3 and TCF4 have been associated with T2D and depression (as well as various other psychiatric traits), an association with CAD has not yet been reported." (PMID 37390107, 2023). "An overlap of these genes with risk genes from major depressive disorder genome‐wide association studies revealed the involvement of the master regulators TCF4 and PAX6 in emotion and reward processing." (PMID 35796185, 2022). "We also sought to identify whether the association of DCC with depression in Europeans were a reflection of its potential LD with TCF4, and examined the distance and LD among SNPs spanning the two genes." (PMID 32184385, 2020). "Tcf4 is implicated in the pathologies of recurrent depressive disorders." (PMID 29375311, 2017). "We also pointed to a genetic association with psychiatric phenomena like psychosis, depression, ADHD, and SUDs, observed through several mutual genes, such as CADM2, TCF4, LINC02758, and CD47, and via genetic correlations." (PMID 40736093, 2025). "Recently, the serum levels of RBFOX1, along with transcription factor 4 (TCF4), have been proposed as potential biomarkers for depression due to their substantially increased levels in unmedicated patients with MDD." (PMID 38399469, 2024). "In line with core symptoms of depression, TCF4 affected subordinate genes positively and negatively correlated with emotional face recognition and PAX6 mainly affected those genes that were negatively correlated with reward processing." (PMID 35796185, 2022). "Three replicated loci were previously reported (ITIH3, FHIT, BAG5), but the other seven (ZNF804A, MIR3143, PSORS1C2, STK19, SPATA31D1, RTN1, TCF4) were novel for depression." (PMID 30626913, 2020). "TCF4 and MEF2C emerged as potentially crucial for CRS-associated depression development." (PMID 38827438, 2024). "Notably, TCF4, NKAPL, ZKSCAN3, ZSCAN16, ZSCAN31 have been associated with depression in previous GWASs." (PMID 36750733, 2023). "The expression of Tcf4 may be significant in the pathomechanism of recurrent depressive disorder." (PMID 33628784, 2021). "The identification of regulatory genes TCF4 and PAX6 thereby implies a potential role of master regulators for functional brain imaging in major depression." (PMID 35796185, 2022). "Therefore, SNPs in DCC are likely genetic risk markers of depression independent of those in TCF4." (PMID 32184385, 2020). "TCF4 and MEF2C are potential therapeutic targets for CRS with depression." (PMID 38827438, 2024).
prostate carcinoma (20 papers, 2005 to 2025). A carcinoma that arises from epithelial cells of the prostate gland. "Therapeutic efficacy using the small molecule inhibitor of β-Catenin Responsive Transcription-3 (iCRT3) that disrupts β-catenin and TCF4 interaction has also been observed in prostate cancer." (PMID 35204808, 2022). "Co-expression of TCF4 and ß-catenin induced transcription of the TOPflash (pGL3-OT) reporter in all three prostate cancer lines, including LNCaP, PC3, and DU145." (PMID 28323888, 2017). "Rs378854 variant reduces binding of the YY1 transcription factor, leading to increased expression of Pvt1 in prostate cancer cell lines while rs6983267 affects binding of the transcription factor TCF4 in CRC cells." (PMID 23240038, 2012). "Previously, we have observed that HOXB13 negatively regulates the expression of TCF4 in prostate cancer cells." (PMID 15928669, 2005). "As observed in prostate cancer cells by another group, two isoforms of TCF4 proteins (∼80 and 60 kDa) were detected in CRC cells." (PMID 15928669, 2005). "In prostate cancer, however, TCF4 is regulated at the transcription level while at the translational suppression in CRC without known mechanism(s)." (PMID 15928669, 2005). "In this study, we present evidence that the Wnt/β-catenin pathway might be activated in prostate cancer cells after androgen-deprivation to promote androgen-independent growth, partly through enhanced interaction of β-catenin with TCF4." (PMID 26509262, 2015). "Moreover, the annotated genes in the constructed network, such as APC, AXIN1, AKT2, CCND2, CAV1, TLE2 and TCF4, are essential regulatory components of these pathways in prostate cancer." (PMID 23782521, 2013). "In prostate cancers, HOXB13 downregulated TCF4 and its responsive genes c-Myc and cyclin D1, subsequently inhibiting cell growth." (PMID 33479226, 2021). "In prostate cancers, HOXB13 negatively regulates β-catenin/TCF4-mediated transactivation and subsequently inhibits cell growth." (PMID 15928669, 2005). "Work described in this manuscript shows that the activity of the Wnt/β-catenin pathway is low in prostate cancer cells likely due to the preference for β-catenin interaction with AR rather than TCF4 in these cells." (PMID 26509262, 2015). "Recent studies in which overexpression of HOXB13 was forced in prostate cancer PC3 cells did, however, indicate that this homeodomain protein has the potential to act as a suppressor of cell growth possibly through modulating the expression of TCF-4." (PMID 15583692, 2005). "Analyses of prostate cancer on xenografts and clinical samples both reveal that SOX9 positively regulates multiple WNT pathway genes, including frizzled (FZD), lipoprotein receptor-related protein (LRP) family members, and the downstream β-catenin effector TCF4." (PMID 28279198, 2017). "The promoter of TRPM4 that is functional in prostate tissues and prostate cancer did not possess clustered binding sites for ERG, AR, TCF4 or Slug but did have multiple binding sites for SMAD transcription factors, suggesting dominant regulation by the TGFβ pathway." (PMID 40332161, 2025).
autism spectrum disorder (18 papers, 2016 to 2026). A spectrum of developmental disorders that includes autism, and Asperger syndrome. "Since Tcf4 is implicated in autism spectrum disorder, we first tested social behaviour wherein we assessed (a) sociable nature and (b) short-term social memory." (PMID 34564703, 2021). "Haploinsufficiency leads to severe intellectual disability and retardation in the Pitt-Hopkins-Syndrome type of autism spectrum disorder and more 5′ located risk alleles associated with long TCF4 isoforms influence performance in certain cognitive tasks." (PMID 33519394, 2020). "Mutations in Da human ortholog TCF4 cause a severe autism spectrum disorder PTHS." (PMID 41500834, 2026).
Cognitive impairment (16 papers, 2015 to 2025). Abnormal cognition is characterized by deficits in thinking, reasoning, or remembering. "Mice moderately overexpressing Tcf4 (Tcf4tg) or with a depletion of the long variants of the TCF4 protein (Tcf4Ex4δ+/−) were both shown to display cognitive impairments, suggesting an inverted U-shape relationship of cognitive function and Tcf4 gene dosage." (PMID 36171421, 2022). "Furthermore, our analysis of the correlation between Tcf4 and Dcx/Synpr genes in the InN6 subpopulation provides strong evidence supporting the association between the In6 subpopulation and cognitive impairment." (PMID 39635132, 2024). "Further analysis was conducted to determine whether Tcf4 regulates the upregulated genes associated with cognitive impairment in these subpopulations." (PMID 39635132, 2024). "Acute loss of Tcf4 from mature neurons leads to profound structural and functional changes resulting in higher baseline activity and increased dendritic complexity, leading to cognitive deficits." (PMID 34564703, 2021). "Future study will need to address whether TCF4 loss or dysfunction alters cerebellar anatomy and local circuit function, and if so, whether changes in cerebellar circuit directly cause motor and cognitive deficits." (PMID 32765228, 2020). "Among them, transcription factor Tcf4 showed the most significant correlation with Dcx and Synpr genes in the InN6 subpopulation, suggesting that InN6 plays a crucial role in regulating cognitive impairment from another perspective." (PMID 39635132, 2024). "The extent of cognitive deficits in PTHS suggests that TCF4 dosage is critical for the development of various brain regions, but it remains largely unknown which neural populations develop in a TCF4-dependent fashion." (PMID 29588831, 2018). "In addition, TCF4 is upregulated by loss of function mutations in the SZ candidate MIR137, and overexpression in the forebrain of mice leads to cognitive impairments and deficits in pre-pulse inhibition." (PMID 28321286, 2017). "Cognitive impairments and deficits in pre-pulse inhibition, such as those observed in SCZ, were found in mice over-expressing TCF4 in the forebrain." (PMID 25658856, 2015).
pancreatic cancer (16 papers, 2011 to 2025). "Transcription factor 4 (TCF4) is abnormally expressed in many tumors, such as pancreatic cancer and leukemia." (PMID 32714094, 2020). "CUTL1 drives WNT-5A expression in pancreatic cancer cell lines whereas TCF4 is the most common transcriptional partner of β-catenin." (PMID 24728340, 2014). "Indeed, the chimeric peptide CP-FaP2 or CP-FaP3 interferes with the formation of the FAM83A-β-catenin and β-TCF4 complex, decreasing the stability of β-catenin, and counteracts the oncogenic capability of pancreatic cancer cells in vitro and in vivo." (PMID 36797256, 2023). "β-catenin and TCF4 were noted to be reduced in Linc00261-overexpressing pancreatic cancer cells." (PMID 34178644, 2021). "Overexpression of miR-802 in MiaPaCa pancreatic cancer cells reduced TCF4 protein levels." (PMID 25910082, 2015). "Heatmap analysis in colorectal, stomach, and pancreas cancer patient datasets showed a consistent overlap between LBH overexpression and WNT signaling genes associated with pathway activation, i.e., WNT2, WNT5A, WNT11, LEF1, TCF4 or TCF7, CCTNB1, CCND1, JUN, DKK3." (PMID 37268816, 2023). "Linc00261 inhibited the activation of the β-catenin/TCF4 pathway and cell metastasis by blocking miR-552-5p-induced targeting of FOXO3 in pancreatic cancer cells." (PMID 34178644, 2021). "Considering the nuclear localization of YEATS4 in the pancreatic cancer, we first tested the interaction between YEATS4 and beta-catenin/TCF4 transcriptional machinery." (PMID 28445953, 2017). "Interestingly, the analysis identified enrichment of multiple TFs including TCF4, WT1, CEBPD, CEBPB, SUZ12, and ZFP281 across all stages of pancreatic cancer progression." (PMID 30644396, 2019). "There was a negative relationship of FOXO3 and β-catenin/TCF4 in pancreatic cancer cells." (PMID 34178644, 2021). "In this study, we demonstrated that CB-839 effectively inhibited cell growth in pancreatic cancer cells, but activated the general control nonderepressible 2 (GCN2)-activating transcription factor 4 (ATF4) signaling pathway." (PMID 40223274, 2025).